IL9 (interleukin 9)
Diseases named in the same sentence as IL9 in open-access papers (continued):
Sharing a sentence is not in itself a finding about the gene and the disease.
COVID-19 (continued). "Increased levels of interleukins (IL-1 α, IL-7, IL-17, and IL-18) and chemokines (CCL11, and CXCL1) were found only in the COVID-19-only, whilst PLWH/COVID-19, had increased levels of four different interleukins (IL-5, IL-6, IL-9, and IL-15) and one chemokine (CXCL10) compared to COVID-19-only." (PMID 41516165, 2025). "The mediators CCL3, CCL4, CCL2, CCL5, IL-12, IL-15, IL-1Ra, and PDGF were higher in healthy volunteers, while the mediators CCL11, CXCL10, IL-1b, IL-6, TNF-a, IFN-g, IL-17, IL-9, IL-10, IL-13, FGF-basic, G-CSF, GM-CSF, IL-7, and IL-2 were increased in COVID-19 positive patients." (PMID 37903875, 2023). "Interleukin 9 (IL-9) induces airway inflammation and bronchial hyper responsiveness in respiratory viral illnesses and allergic inflammation, however, IL-9 has not been assigned a pathologic role in COVID-19." (PMID 37429848, 2023). "Importantly, this study revealed a striking low IL-9 level and high IFNγ/IL-9 ratio in the plasma of patients who later died compared to mild and severe cases who recovered, suggesting that this could be an important biomarker for predicting the severity of COVID-19 and post-COVID-19 syndrome." (PMID 37569646, 2023). "We found that acute COVID-19 neutrophils secreted reduced G-CSF, MIP-1α, MIP-1β, MCP-1, IL-2, SDF-1α, IL-9, IL-17A, IL-18, IL-20 and IL-23 levels, but secreted increased soluble PD1, IP-10 and MIP-2α levels compared to rec-phase and healthy neutrophils upon bacterial challenge." (PMID 35007290, 2022). "Research of the literature on the role of IL-9 in COVID-19 showed more interest in IL-9 producing cells and not in the cytokine itself." (PMID 36430621, 2022). "Elevated levels of cytokines such as IL1B, IL7, IL8, IL9, and IL10, monocyte chemoattractant protein and tumor necrosis factor (TNF), among others, in COVID-19 have been reported and elevated proinflammatory cytokine levels have been found to correlate with disease severity." (PMID 35172279, 2022). "IL-9 and TSLP could be other targets to inhibit Th2 responses in COVID-19 patients, as these molecules promote allergic inflammation (Temann and others 2002; Ito and others 2012; Koch and others 2017)." (PMID 35674675, 2022). "Similarly, FGF-2, FLT-3L, IL-9, IL-17E/IL-25, IP-10, MCP-3, and MIP-1β were also positively correlated with SOFA scores in COVID-19 patients." (PMID 34131192, 2021). "Our data further demonstrated a smoking-induced increase in serum furin and inflammatory cytokine [IFNγ(p = 0.0836), Eotaxin (p < 0.05), MCP-1 (p < 0.05), and IL-9 (p = 0.0991)] levels in COVID-19 patients as compared to non-smoking controls." (PMID 34122129, 2021). "In patients with COVID-19 hospitalized in intensive care units, elevated serum levels of IL-1β, IL-7, IL10, IL-17, IL-2, IL-9, Th17, IFN-γ, GM-CSF, G-CSF, IL-8, TNF-α, MIP1B, MCP1, MIP1A, and IP10 were observed, suggesting that the relation between periodontitis and COVID-19 may be established." (PMID 34068221, 2021). "Some type 2 cytokines (IL-4, IL-9, IL-13, etc.)have inhibitory effects on the production of proinflammatory cytokines (IL-1β, IL-6, TNF-α, etc.), the overactivation of which have been proposed as a potential key mechanism of protection against COVID-19 to some extent." (PMID 35082829, 2021). "Furthermore, we found a moderate increase in the levels of IL-9 (p = 0.0991) amongst smokers infected with COVID-19 compared to COVID-19 positive non-smokers." (PMID 34122129, 2021). "Intriguingly, levels of IL-9, eotaxin, MIP-1β, and RANTES in patients who recovered from COVID-19 were found to be the lowest among the 3 groups, further indicating that cytokine levels are dysregulated in patients with COVID-19 after clinical symptom remission." (PMID 34784300, 2021). "IL-27, IL-9, IL-12p40, and MCP-3 seemed significant in non-Severe samples, and other studies have reported aberrant levels of these cytokines in COVID-19 patients." (PMID 37015978, 2023).
COVID-19 (continued). "We investigated the circulating levels of IFNγ, IL-4, sIL-4R, IL-5, IL-9, IL-17A, IL-17F, IL17-E/25, IL-22 and sCD30 in surviving and non-surviving severe COVID-19 patients and healthy controls." (PMID 36142255, 2022). "Notably, increased levels of IL-9 (p = 0.0305), IP-10 (p = 0.0069), MCP-1 (p = 0.0275) and RANTES (p = 0.0370) were observed in COVID-19 patients compared to SARS-CoV-2 negative subjects (respectively)." (PMID 39061002, 2024). "Whether GRO-a, IL-9, TNF-α and TNF-β play protective roles in COVID-19 has not been eliminated at present, which needs further confirmation by basic experiments." (PMID 34489933, 2021). "Further, IL-4, IL-9, CCL5, CCL8, GM-CSF, and PDGF are exclusively induced by SARS-CoV-2 and these differences may explain why multi-organ injury including testicular damage and long-term sequelae is observed in COVID-19 patients and not with influenza virus." (PMID 37200377, 2023).
autoimmune disease (52 papers, 2011 to 2025). A disorder resulting from loss of function or tissue destruction of an organ or multiple organs, arising from humoral or cellular immune responses of the individual to their own tissue constituents. "In recent years, Th9 cells, along with the related inflammatory cytokine IL-9 and its associated transcription factors, have been extensively studied in various autoimmune diseases." (PMID 40771819, 2025). "These responses culminate in the production of a plethora of cytokines such as TSLP, IL-9, IL-25, and IL-33, which have been implicated in the pathogenesis of several inflammatory and autoimmune diseases." (PMID 37063828, 2023). "It is known that IL-9-producing CD4(+) T cells and IL-9 are associated with inflammatory bowel disease, tumor, and autoimmune diseases." (PMID 33941281, 2021). "Few studies have evaluated the expression of Th9 cells or the levels of IL-9 in patients with autoimmune diseases, and it is unclear if there is an association with the pathogenesis of these diseases or if it is just an epiphenomenon." (PMID 26078482, 2015). "IL-9 is a pro-inflammatory factor associated with autoimmune diseases." (PMID 37221406, 2023). "The variants associated with different binding sites PU.1 were the molecular basis for genetically-induced cellular differences and susceptibility to autoimmune diseases.PU.1 is a key regulator of the phenotype of IL-9-secreting T cells and is important for the development of inflammation." (PMID 36248862, 2022). "Additionally, involvement of IL-9 has also been observed in the development of autoimmune diseases and its deficiency lessens the disease progression." (PMID 31936604, 2020). "Inhibiting IL-9 may have wider impact on the production of pathogenic cytokines involved in autoimmune diseases including RA and may offer better control over the disease." (PMID 29382374, 2018). "Several recent discoveries of Th9 cells found in mice and human have broadened our understanding of autoimmune disease, because this unique IL-9-producing subset seems can explain some phenomena underlying T cell-mediated tissue inflammation and antiviral immunities." (PMID 21635745, 2011). "Furthermore, IL-9 might be involved in the development of autoimmune disease through Th17-associated inflammation and vasculopathy." (PMID 36117047, 2022). "Collectively, these findings support the potential of targeting Th9/IL-9 in autoimmune diseases; however, clinical trials are needed to evaluate its efficacy and safety across various autoimmune conditions." (PMID 40771819, 2025). "IL-9 has been proposed as a key driver of immune responses in chronic inflammatory and autoimmune diseases at mucosal surfaces." (PMID 39466030, 2024). "IL-9 and IL-9-producing T-cells (termed Th/Tc9), are mainly introduced as pro-inflammatory mediators involved in the pathogenesis of a variety of autoimmune diseases and allergic inflammations." (PMID 37835465, 2023). "Due to the pleiotropic effects, IL-9 has been proven to participate in diverse diseases, including cancer, autoimmune diseases, and other pathogen-mediated immune regulatory diseases." (PMID 35211408, 2022). "IL9R is a receptor of interleukin 9 (IL-9), which participates in various models of T cell-dependent inflammation and plays an important role in driving the immune responses to autoimmune diseases and chronic inflammation on mucosal surfaces." (PMID 36118358, 2022). "Interleukin 9 (IL-9)-producing helper T (Th9) cells are essential for inducing anti-tumor immunity and inflammation in allergic and autoimmune diseases." (PMID 34075041, 2021). "Otherwise, few diseases/conditions were reported, and elevated IL-9 levels were found in asthmatic patients, patients with allergic rhinitis and a peanut allergy, and those suffering from some autoimmune diseases." (PMID 33953642, 2021).
autoimmune disease (continued). "The overexpression of IL-9 and IL-9Rα in interstitial fluids and tissues isolated from patients with autoimmune diseases has been related to the degree of tissue inflammation." (PMID 34944921, 2021). "It is noteworthy that IL-9 expression also ameliorates the outcomes of some types of autoimmune diseases." (PMID 34944921, 2021). "It has been reported that Th9 cells are related to autoimmune diseases by secreting IL-9, such as systemic lupus erythematosus (SLE), allergic asthma, ulcerative colitis (UC), and rheumatoid arthritis (RA)." (PMID 32455141, 2020). "Although the research on Th9 cells is not comprehensive, evidence is accumulated to demonstrate a role of IL-9 and Th9 cells in the pathogenesis of a spectrum of autoimmune diseases." (PMID 32455141, 2020). "Role of Th9 cells and interleukin-9 (IL-9) in human autoimmune diseases such as psoriasis and ulcerative colitis has been explored only very recently." (PMID 29382374, 2018). "IL-9 neutralization has been effective in other models of autoimmune disease, including experimental autoimmune encephalitis (EAE)." (PMID 23335955, 2013). "Previous studies have shown that IL-9 plays a pro-inflammatory role during the development of autoimmune disease." (PMID 23119059, 2012). "It has been shown that IL-9 plays a proinflammatory role in the pathogenesis of certain autoimmune diseases." (PMID 23119059, 2012). "Moreover, most current functional studies have been conducted in animal models, whereas data on IL-9 expression, transcription factor profiles, and Th9 cell distribution in human autoimmune diseases are primarily derived from case–control studies." (PMID 40771819, 2025). "Targeting the Th9/IL-9 axis is a promising approach for immunotherapy in autoimmune diseases." (PMID 40771819, 2025). "Moreover, overexpression of IL-9 and IL-9Rα in interstitial fluids and tissues isolated from patients with autoimmune diseases has been related to the degree of tissue inflammation." (PMID 39281678, 2024). "On the other hand, IL-9 expression exerts an anti-inflammatory activity in some types of autoimmune diseases, such as multiple sclerosis, where it impairs the secretion of Granulocyte-Macrophage Colony-Stimulating Factor (GM-CSF) by CD4+ T cells, thereby reducing autoimmune neuroinflammation." (PMID 39281678, 2024). "Several studies have indicated that IL-9 is a cytokine commonly associated with inflammatory, allergic, and autoimmune diseases as well as parasitic infections and lack of IL-9 prolongs inflammation resolution in models of arthritis and ulcerative colitis." (PMID 37920237, 2023). "Interleukin-9 (IL-9) is a multipotent cytokine that acts on a variety of immune cells by binding to the IL-9 receptor (IL-9R) and is involved in a variety of diseases such as cancer, autoimmune diseases, and other pathogen-mediated immune regulatory diseases." (PMID 35211408, 2022). "IL-9 mediates several types of inflammation in autoimmune diseases." (PMID 33671196, 2021). "Neutralization of anti-IL-9 antibody reduces the titer of autoantibody and reduces the inflammatory response in vivo, suggesting that IL-9 may be a therapeutic target for autoimmune diseases." (PMID 32455141, 2020). "This anti-inflammatory function of IL-9 on macrophages could be relevant for the damping of exaggerated inflammation, observed in autoimmune diseases and even serve as target for future therapeutic avenues." (PMID 32375811, 2020). "IL-9 play important roles in a broad spectrum of autoimmune diseases and allergic inflammation." (PMID 30139984, 2018). "IL-9 has been demonstrated to play a role in models of autoimmune disease such as EAE." (PMID 23335955, 2013). "This raises the possibility that similar than targeting cytokines such as TNF-α, IL-12/23, IL-17, or IL-21 blocking of IL-9 might be of potential benefit in patients with psoriasis and other Th17 cell-mediated autoimmune diseases." (PMID 23335955, 2013).
autoimmune disease (continued). "Anti–IL-9 mAb treatment may provide an effective therapeutic strategy against autoimmune diseases." (PMID 36248862, 2022). "Accordingly, IL-9-producing CD4(+) T cells and IL-9 appear to be new therapeutic targets in allergic or autoimmune diseases." (PMID 33941281, 2021). "On the other side, IL-9 is a cytokine produced primarily by CD4+ Th9 cells and is generally reported to mediate allergic and autoimmune diseases." (PMID 29967565, 2018). "Both IL-9 and TNF-β are known to be involved in the inflammatory response in many autoimmune diseases, and MIP-1b and RANTES could chemoattract monocytes/macrophages and T cells to the target site." (PMID 38729610, 2024). "Last but not least, Th9 cells and IL-9 are pro-inflammatory factors and are closely related to autoimmune diseases such as SLE, MS, IBD, RA and psoriasis." (PMID 32508847, 2020). "Despite the broad ability of IL-9 to impact multiple types of inflammation, it is not clear how it functions in the context of autoimmune diseases." (PMID 26078482, 2015). "Furthermore, the contribution of cytokines such as IL-2Rα, IL-9, and TNF-β, which are known to be involved in inflammatory and autoimmune diseases, to the pathogenesis of PE remain unknown." (PMID 37718445, 2023).
melanoma (49 papers, 2014 to 2025). A malignant, usually aggressive tumor composed of atypical, neoplastic melanocytes. "The absence of RORγ, a critical component of the proinflammatory type 17 T helper (Th17) cell pathway, results in elevated IL-9 production by T cells, a phenomenon which is associated with significant suppression of melanoma growth in murine melanoma models." (PMID 39518891, 2024). "Antibiotic treatment promoted the growth of melanoma lung foci and it was associated with decreased IL-9+ T-cell infiltration." (PMID 37189417, 2023). "It confirmed that in this melanoma model, tumor growth accelerated by disbalance in the microbiota was largely caused by IL-9 deficiency in the TME." (PMID 37189417, 2023). "In a melanoma model, IL-9 deficiency promoted tumor growth, whereas IL-9 treatment decreased metastasis." (PMID 32117199, 2019). "In another study, RORγ-deficient mice showed inhibited melanoma growth, and this effect was identified to be IL-9 dependent." (PMID 29904382, 2018). "The role of IL-9 in preventing melanoma cell growth was further explored in IL-9 receptor-deficient mice, and it was found that B16 tumor cells featured faster growth in vivo in the absence of IL-9 receptor signaling." (PMID 27832300, 2017). "IL9 has been demonstrated to enhance the survival and function of human melanoma cells, increasing their cytotoxic activity against these cells, which were confirmed in our analysis." (PMID 41148223, 2025). "For instance, IL-9 directly induces apoptosis and suppresses proliferation in melanoma, enhances CD8 T cell cytotoxicity, and improves mast cell anti-tumor activity." (PMID 41030439, 2025). "This protection against ferroptosis in the tumor environment highlights the potential of targeting the IL-9/STAT3/fatty acid oxidation pathway to enhance T cell –based therapies for melanoma." (PMID 40636453, 2025). "Regarding the potential therapeutic use of the findings, there is evidence of anti-metastatic effects of IL-9 in melanomas." (PMID 40954493, 2025). "IL-9 boosts melanoma progression by improving the metabolism and survival of Tc9 cells, which secrete IL-9." (PMID 40636453, 2025). "In contrast, melanoma cell lines upregulate anti-proliferative (p21) or pro-apoptotic (TRAIL) molecules in response to IL-9, enhancing apoptosis." (PMID 41030439, 2025). "IL-9 enhances the effectiveness of T cells in melanoma treatment through engineered chimeric receptors." (PMID 40636453, 2025). "On the other side, IL-9 has also been shown to have antitumor roles in the development of melanoma, lung carcinoma, and colon cancers." (PMID 38473379, 2024). "IL-9 antibody treatment promoted B16 melanoma lung metastasis, while recombinant IL-9 treatment inhibited B16 melanoma and Lewis lung cancer growth in mice." (PMID 38473379, 2024). "In murine melanoma experiments, the increase in both the quantity of Th9 cells and IL-9 significantly reduces the tumor growth rate, despite in vitro studies demonstrating a close association with their indirect effects." (PMID 38840908, 2024). "Similar findings were observed in mouse melanoma models, where in vivo IL-9 blockade promoted melanoma progression, while on the other hand recombinant IL-9 enhanced the cytotoxic ability of murine melanoma-specific CD8+ T cells." (PMID 39281678, 2024). "The results suggest that the enrichment of TAMs and IL9 in the TME evoked effective antitumor activity against B16F10 melanoma." (PMID 36968220, 2023). "Overall, although IL-9 plays a beneficial role in some cancers (such as melanoma) by inducing not only innate immunity but also adaptive immunity, its tumor-promoting and inflammatory effects limit its clinical development." (PMID 36936961, 2023). "A very recent study on B16 melanoma metastasis showed that IL9 from CD4+ T cells exerted protumor functions by inducing the expression of Arg1, an M2 marker, in pulmonary interstitial macrophages." (PMID 36968220, 2023).